GCG (glucagon)
Description:
[Glucagon]: Plays a key role in glucose metabolism and homeostasis. Regulates blood glucose by increasing gluconeogenesis and decreasing glycolysis. A counterregulatory hormone of insulin, raises plasma glucose levels in response to insulin-induced hypoglycemia. Plays an important role in initiating and maintaining hyperglycemic conditions in diabetes. Binds to and activates the glucagon receptor GCGR, which couples to the G(s) G protein and elevates intracellular cAMP, triggering downstream metabolic responses. [Glucagon-like peptide 1]: Potent stimulator of glucose-dependent insulin release. Also stimulates insulin release in response to IL6. Plays important roles on gastric motility and the suppression of plasma glucagon levels. May be involved in the suppression of satiety and stimulation of glucose disposal in peripheral tissues, independent of the actions of insulin. Has growth-promoting activities on intestinal epithelium. May also regulate the hypothalamic pituitary axis (HPA) via effects on LH, TSH, CRH, oxytocin, and vasopressin secretion. Increases islet mass through stimulation of islet neogenesis and pancreatic beta cell proliferation. Inhibits beta cell apoptosis. [Glucagon-like peptide 2]: Stimulates intestinal growth and up-regulates villus height in the small intestine, concomitant with increased crypt cell proliferation and decreased enterocyte apoptosis. The gastrointestinal tract, from the stomach to the colon is the principal target for GLP-2 action. Plays a key role in nutrient homeostasis, enhancing nutrient assimilation through enhanced gastrointestinal function, as well as increasing nutrient disposal. Stimulates intestinal glucose transport and decreases mucosal permeability. [Oxyntomodulin]: Significantly reduces food intake. Inhibits gastric emptying in humans. Suppression of gastric emptying may lead to increased gastric distension, which may contribute to satiety by causing a sensation of fullness. [Glicentin]: May modulate gastric acid secretion and the gastro-pyloro-duodenal activity. May play an important role in intestinal mucosal growth in the early period of life.
Synonyms: GRPP; GLP-1; GLP1; GLP2
Tractability: Small molecule: a structure with a bound ligand is known; a high-quality ligand is known. Antibody: UniProt places it where antibodies can reach, with high confidence; its Gene Ontology location is reachable by antibodies, with high confidence; UniProt predicts a signal peptide or a membrane-spanning region. PROTAC: a small molecule that binds it is known.
Target class: Secreted protein
Gene: Protein-coding gene on chromosome 2 (162,142,882 to 162,152,404, reverse strand). Ensembl gene ENSG00000115263.
Subcellular location: Secreted; Secreted (Glucagon-like peptide 1)
Subcellular location (Human Protein Atlas): Endoplasmic reticulum; Vesicles; Predicted to be secreted
Pathways (Reactome):
Signal Transduction: G alpha (q) signalling events; G alpha (s) signalling events; Glucagon-type ligand receptors
Metabolism: Glucagon signaling in metabolic regulation; Glucagon-like Peptide-1 (GLP1) regulates insulin secretion
Metabolism of proteins: Synthesis, secretion, and deacylation of Ghrelin; Synthesis, secretion, and inactivation of Glucagon-like Peptide-1 (GLP-1)
Gene Ontology:
Molecular function: identical protein binding; protein binding; glucagon receptor binding; hormone activity; receptor ligand activity; signaling receptor binding
Biological process: adenylate cyclase-modulating G protein-coupled receptor signaling pathway; feeding behavior; G protein-coupled receptor signaling pathway; glucose homeostasis; intracellular glucose homeostasis; positive regulation of gluconeogenesis; positive regulation of insulin secretion; positive regulation of insulin secretion involved in cellular response to glucose stimulus; regulation of insulin secretion; response to activity; adenylate cyclase-activating G protein-coupled receptor signaling pathway; cellular response to glucagon stimulus; negative regulation of apoptotic process; positive regulation of calcium ion import; positive regulation of ERK1 and ERK2 cascade
Cellular component: extracellular region; endoplasmic reticulum lumen; secretory granule lumen; cytoplasm; plasma membrane
Genetic constraint (gnomAD): Loss-of-function variants: 6 observed, 12.56 expected, observed/expected ratio (o/e) 0.48, 90% interval 0.26 to 0.94. The upper end of that interval is the gene's LOEUF score, 0.94, which puts it in group 4 of 6, group 1 being the genes least tolerant of losing a copy. Missense variants: 89 observed, 97.89 expected, observed/expected ratio (o/e) 0.91, 90% interval 0.76 to 1.08. Synonymous variants: 32 observed, 33.94 expected, observed/expected ratio (o/e) 0.94, 90% interval 0.71 to 1.27.
Homologues: Orthologues: chimpanzee GCG (100% identical), macaque GCG (97% identical), dog GCG (94% identical), rabbit GCG (93% identical), guinea pig GCG (92% identical), pig GCG (91% identical), rat Gcg (91% identical), mouse Gcg (90% identical), tropical clawed frog gcg (54% identical), zebrafish gcgb (40% identical), zebrafish gcga (33% identical).
Diseases named in the same sentence as GCG in open-access papers:
GCG is named in the same sentence as 480 diseases in open-access papers, as found by Europe PMC text mining. Sharing a sentence is not in itself a finding about the gene and the disease. The quoted sentences say what the papers report.
diabetes (1,203 papers, 1998 to 2026). "For example, SARS-CoV-2 infection of beta cells, which has been proposed to increase the risk for developing diabetes, induces beta cell transdifferentiation leading to increased expression of alpha cell markers in beta cells including GCG." (PMID 41291239, 2026). "Diabetes is a disease associated with an increase in the glucagon/insulin ratio in terms of the biological activity of these two hormones, and hence with an increase in cellular levels of cAMP and a decrease in cellular levels of succinyl-CoA." (PMID 40305364, 2025). "Elevated levels of plasma corticosterone and glucagon levels have each been reported in diabetic Lepob/ob mice and both are implicated in diabetes pathogenesis." (PMID 40371641, 2025). "While diabetes has traditionally been characterized by insulin deficiency or resistance, accumulating evidence suggests that hyperglucagonemia and impaired glucagon signaling are equally critical contributors to its pathogenesis." (PMID 40822953, 2025). "Analyzing diabetes‐related hormones such as insulin and glucagon using conventional enzyme‐linked immunosorbent assay (ELISA) has been the gold standard." (PMID 40278502, 2025). "American Diabetes Association (ADA) recommends the utilization of glucagon in all individuals who are at clinical risk of hypoglycemia (<54 mg/dL)." (PMID 40585626, 2025). "We also tested diabetes associated indicators and observed decreased glucagon and PAI-1 and increased insulin levels, suggesting nicotine restored glucose disposal ability." (PMID 41488304, 2025). "Emerging evidence suggests that hyperglucagonemia is more strongly associated with obesity and NAFLD than with diabetes itself; elevated fasting glucagon levels have been observed even in individuals with obesity and normal glucose tolerance." (PMID 41149695, 2025). "Immunostaining of pancreatic islets demonstrated that Car@PLGA-NPs effectively reversed diabetes-associated hormonal dysregulation: significantly increasing depleted insulin levels and decreasing elevated glucagon levels in db/db mice (P < 0.001)." (PMID 41586316, 2025). "On the other hand, within the field of diabetes, previous studies have begun to focus on the association between glucagon and microvascular complications." (PMID 41458542, 2025). "Glucagonomas produce excess glucagon with symptoms including diabetes, weight loss, and necrolytic migratory erythema (skin rash)." (PMID 40144450, 2025). "Type 3c diabetes mellitus is a secondary form of diabetes associated with pancreatic disease, primarily chronic pancreatitis, which impairs insulin and glucagon secretion, resulting in inadequate glycemic control." (PMID 40401174, 2025). "The American Diabetes Association defines diabetes as a condition marked by the degeneration of insulin- and glucagon-producing cells." (PMID 39598390, 2024). "Inadequate water intake induces elevated levels of vasopressin, which stimulates vasopressin V1b receptors on the pancreatic islets, thereby causing increased levels of glucagon and adrenocorticotropic hormone, and thus ultimately leading to diabetes." (PMID 38892576, 2024). "Diabetes is accompanied by glucagonemia, and glucagon excess is more critical to the development of diabetes than insulin deficiency." (PMID 39125959, 2024). "Consuming a large amount of animal protein can cause insulin resistance by stimulating the release of glucagon in both healthy people and individuals with diabetes, making it harder to control their metabolism." (PMID 38800782, 2024). "Conditions with chronically increased glucagon levels can lead to acinar atrophy, such as in diabetes with insulin deficiency or, less commonly, in glucagonomas." (PMID 38398492, 2024). "In 1974, Mallinson coined the term “glucagonoma syndrome” for a constellation of symptoms including NME, perioral dermatitis, glossitis, diabetes, anemia, and weight loss, attributed to the over-secretion of glucagon." (PMID 39252948, 2024).
diabetes (continued). "Nevertheless, we did observe higher fasting glucagon in subjects with diabetes-associated variation at rs10830963." (PMID 39011323, 2024). "Dysregulated glucagon secretion and inadequate functional beta cell mass are hallmark features of diabetes." (PMID 39433176, 2024). "This increase in alpha cells likely exacerbates the detrimental effects of diabetes as insulin resistance combined with increased glucagon promotes hyperglycemia and diabetes-associated metabolic dysregulation." (PMID 39683552, 2024). "It leads to pancreatic damage and causes diabetes by reprogramming cells to produce more glucagon and less insulin." (PMID 39099965, 2024). "Hyperglycaemia that occurs in individuals with type 2 diabetes mellitus is caused by different abnormalities such as an impaired insulin secretion, GCG secretion, glucose uptake/utilisation/reabsorption or lipotoxicity." (PMID 38503901, 2024). "It has been proven that, diabetes in the course of CP is accompanied by concomitant insulin, glucagon, and pancreatic polypeptide (PP) deficiency." (PMID 39596226, 2024). "The presenting symptoms of glucagonomas are secondary to their secretion of glucagon, with associated diabetes, weight loss, and characteristic rash of necrolytic migratory erythema." (PMID 37046665, 2023). "That said, increased islet content (ex vivo) and secretion (in situ and in vitro) of SST under low glucose conditions have long implicated SST in the pathogenesis of defective glucagon counterregulation in animal models of diabetes." (PMID 38298268, 2023). "Since manifest diabetes is associated with increased fasting plasma glucose in the presence of increased plasma glucagon, the inhibition of glucagon release is partially lost." (PMID 37764697, 2023). "The importance of glucagon in the fasting-associated glucose secretion and pathogenesis of diabetes is well characterized." (PMID 36866247, 2023). "The hypersecretion of glucagon with its catabolic effect, in association with the malnutrition resulting from diarrhea, can result in the onset or worsening of already established diabetes." (PMID 37628857, 2023). "Nevertheless, the tight control of hormonal regulations, including, by insulin and glucagon, ensure the proper function of neonatal liver with minimal risk of developing diabetes despite the high metabolic load." (PMID 37826876, 2023). "Elevation of glucagon levels and increase in α cell proliferation is associated with states of hyperglycemia in diabetes." (PMID 37140984, 2023). "High fasting levels of glucagon are associated with the diagnosis of glucagonoma leading to a typical triad of glucagonoma syndrome (skin rash, diabetes mellitus, and weight loss)." (PMID 37685358, 2023). "Diabetes mellitus is a group of metabolic disorders characterized by hyperglycemia caused by resistance to insulin action, inadequate insulin secretion, or excessive glucagon production." (PMID 36770960, 2023). "Long diabetes duration is considered to be a risk factor for defective glucose counter-regulation in T1D subjects, with impaired glucagon secretion as an important mechanism." (PMID 37174997, 2023). "McGavran and his colleagues identified in 1966 a metastatic tumor of the pancreatic islets, which was associated with the clinical picture present in diabetes and dermatitis but also with high levels of glucagon in the blood." (PMID 37628857, 2023). "Counterregulation of plasma glucose by insulin and glucagon is a well-characterized phenomenon in normal physiology, while dysregulation of these hormones leads to dysglycemia and is a hallmark of diabetes." (PMID 37660302, 2023). "Although GCGR and glucagon play important roles in diabetes, the mechanisms and role of mutations still needs to be explored." (PMID 35784565, 2022). "Fasting hyperglucagonemia and uncontrolled glucagon levels after meals increase hepatic glucose production and further aggravate diabetes-associated complications." (PMID 36104518, 2022).
diabetes (continued). "One likely cause of the hyperglycemia of diabetes is the excessive production of glucagon, or hyperglucagonemia, which reflects dysregulated glucagon secretion from α-cells." (PMID 34923907, 2022). "To examine the underlying mechanisms of the endo-lysosomal system in glucagon trafficking in diabetes, we cultured αTC1-6 cells in media containing 16.7 mM glucose for 2 weeks, then treated them with Bafilomycin A1 (BFA1) for 2 h to inhibit lysosomal activity." (PMID 34923907, 2022). "We assessed the polygenic risk score for type 2 diabetes, age at onset of diabetes and measures of body composition, as well as plasma glucose, serum insulin, proinsulin, C-peptide, glucagon and NEFA response during the OGTT." (PMID 34951657, 2022). "Aberrant glucagon secretion and signaling is a hallmark of both type 2 (insulin resistant) and type 1 (insulin deficient) diabetes." (PMID 36002172, 2022). "While glucagon is primarily released from α-cells, which enhance insulin secretion, the role of glucagon and α-cells and their associations with proinsulin levels in diabetes progression need to be evaluated in future studies." (PMID 35887628, 2022). "Fasting hyperglycemia in diabetes mellitus is caused by unregulated glucagon secretion that activates gluconeogenesis (GNG) and increases the use of pyruvate, lactate, amino acids, and glycerol." (PMID 36402444, 2022). "Diabetes mellitus is often associated with paradoxical postprandial hyperglucagonemia; like insulin, amylin was shown to inhibit glucagon release, which therefore generates a preference for glucose accretion via meal-related glucose over endogenous stores." (PMID 35456307, 2022). "We also found an increased glucagon expression, a hallmark of diabetes, which led to worsening of the hyperglycemia in the islet of mice deficient in CBS." (PMID 35681432, 2022). "Impaired α-cell function has been recently introduced as a pathophysiological factor for diabetes development which has been linked to dysregulation of glucagon secretion." (PMID 35887628, 2022). "By targeting alpha cells in the pancreas, EDCs disrupt molecular signals, which in turn induces glucagon release when blood glucose levels are low, consequently increasing the risk of diabetes." (PMID 35096073, 2022). "Diabetes is a risk factor for liver cancer development and is commonly characterized by abnormally high glucagon signaling, likely as a result of decreased insulin sensitivity." (PMID 35123542, 2022). "In patients with diabetes with relatively steady levels of insulin, a rise in glucagon causes hyperglycemia and glycosuria." (PMID 35784565, 2022). "In this review, we explore the controversial relationships between glucagon and metabolic disorders associated with diabetes based on recent research with an emphasis on recent evidence supporting the important role of glucagon." (PMID 35784565, 2022). "Although a defective glucagon secretory response causes various problems in patients with diabetes, the mechanisms involved in pancreatic α-cell physiology remain elusive, unlike those in β cell physiology, which have been widely studied." (PMID 36104518, 2022). "Further studies are needed to determine the effect of hepatic glucagon resistance on metabolic disorders and its association with the occurrence of diabetes." (PMID 35784565, 2022). "We found that male offspring are more susceptible than females to diabetes risk in adulthood, possibly due to altered metabolic regulations of insulin, ghrelin, and glucagon during their early life." (PMID 36109770, 2022). "Diabetes mellitus is caused by breakdown of blood glucose homeostasis, which is maintained by an exquisite balance between insulin and glucagon produced respectively by pancreatic beta cells and alpha cells." (PMID 33428669, 2021). "GCG, or the proglucagon gene, causes plasma glucose to rise in response to insulin-induced hypoglycemia and maintains the hyperglycemic condition in diabetes." (PMID 35154608, 2021).